HNF4A (hepatocyte nuclear factor 4 alpha)
Diseases named in the same sentence as HNF4A in open-access papers (continued):
Sharing a sentence is not in itself a finding about the gene and the disease.
Hepatic steatosis (continued). "However, it can aggravate hepatic steatosis, so it is necessary to study the optimal timing of HNF4α inhibition and the development of surrogate markers that can predict it." (PMID 36362837, 2022). "Therefore, we conclude hepatic PRMT1 ameliorate diet-induced hepatic steatosis via induction of PGC-1α expression by methylation of transcription factor HNF-4α." (PMID 35401831, 2022). "An early study has identified that RARα overexpression alleviated hepatic steatosis via suppressing HNF4α-regulated PPARγ expression, but whether CD36 is involved in RARα’s regulation on hepatic lipid metabolism is unknown." (PMID 35745142, 2022). "Previous study reported that HNF4α could prevent liver steatosis by controlling hepatic carboxylesterase 2 expression and modulating lipolysis, lipogenesis, and endoplasmic reticulum in NAFLD." (PMID 33415161, 2020). "Moreover, knockout of HNF-4α induces liver steatosis in mouse models, similar to that seen after PFOS treatment." (PMID 29860686, 2018). "HNF4α may prevent hepatic stellate cell activation and thus ameliorate liver steatosis through transactivation of PPARγ." (PMID 22190905, 2011). "In addition, recent studies have implicated HNF4A and PROX1-AS1 in insulin resistance and T2D, whereas loci harboring FAM13A, RSPO3, and EBPL have been associated with body fat distribution and hepatic steatosis." (PMID 39796632, 2025). "HNF4α is an orphan nuclear receptor that is a master regulator of hepatic development and function, including genes involved in triacylglycerol, cholesterol, and lipoprotein metabolism, and HNF4α is thought to play a central role in the development of fatty liver disease." (PMID 40863113, 2025). "Thus, GR and HNF4α cooperatively protect against HFHS-induced fatty liver and hyperlipidemia." (PMID 35614477, 2022). "In line with this, another study documented that PRMT1 was found to induce PGC-1α mRNA expression through the recruitment of HNF-4α to the promoter region of PGC-1α, thereby attenuating hepatic steatosis via enhancing PGC-1α-mediated fatty acid oxidation." (PMID 39871927, 2022). "Mechanistically, methyltransferase activity of PRMT1 was required to induce PGC-1α mRNA expression via recruitment of HNF-4α to the promoter of PGC-1α, and hence attenuated HFD-induced hepatic steatosis by enhancing PGC-1α-mediated fatty acid oxidation." (PMID 35401831, 2022). "Finally, the HNF4α agonist, NCT, reduces sepsis lethality by limiting hepatic steatosis and organ dysfunction and improving hepatic APR." (PMID 39261648, 2024). "induction of lipid catabolic genes and suppression of lipogenic genes by HNF4α and GR may mediate the early resistance to HFHS-induced fatty liver and hyperlipidemia." (PMID 35614477, 2022). "Although the activating ligand for HNF4α has not been identified, small activating RNA for HNF4α has been used to successfully induce HNF4α and ameliorate hyperlipidemia and fatty liver in HFD-fed rats." (PMID 35614477, 2022). "Next, we examined whether the HNF4α levels were significantly downregulated and/or the PPARγ levels were upregulated in the case of NASH, a more severe stage of fatty liver disease." (PMID 32235813, 2020). "Our results revealed that HNF4α and SHBG mRNAs were significantly lower in subjects with high grades of hepatic steatosis, in accordance with a significantly decreasing trend in serum SHBG levels along with the elevated severity in our NAFLD subjects diagnosed by ultrasonography." (PMID 30455723, 2018). "Surprisingly, we did not observe any significant change in hepatic steatosis in Ad-HNF4α-treated rats." (PMID 22190905, 2011). "When the activation of PPARα signaling is impaired by fructose overdose, the cooperative induction of lipid catabolic genes and suppression of lipogenic genes by HNF4α and GR may play a key role in the early resistance to HFHS-induced fatty liver and hyperlipidemia (Graphical abstract)." (PMID 35614477, 2022).
Hepatic steatosis (continued). "We are suggesting that hepatic HNF4α inhibition can attenuate bile acid toxicity and be more effective as a therapeutic strategy in NAFLD patients; however, it is necessary to study the optimal timing of HNF4α inhibition due to the worsening of hepatic steatosis." (PMID 36362837, 2022).
steatosis (38 papers, 2009 to 2025). Increased lipid within the cytoplasm of cells. "The ablation of hepatic HNF4α gene expression causes steatosis with a disturbed lipid profile and an upregulated expression of inflammatory genes." (PMID 35723304, 2022). "The conditional liver-specific HNF4α disruption in mice led to severe steatosis and reduced serum triglycerides, which were associated with the selective disruption of ApoB and MTTP genes’ expression." (PMID 36362837, 2022). "Liver-specific conditional knockout of HNF4α in adult mice led to severe steatosis associated with disruption of VLDL secretion and misregulation of ApoB and MTTP expression." (PMID 31781248, 2019). "Tissue-specific Hnf4a knock-out (KO) mice revealed that the loss of Hnf4a caused severe hepatomegaly and steatosis with a selective disruption of very-low-density lipoprotein secretion due to decreased expression of genes encoding apolipoprotein B." (PMID 29899848, 2018). "Conversely, serum miRNAs associated with blunt steatosis specifically highlighted activity of FOXO1&HNF4α on CPT2, the lipid droplet and ER-lipid-raft associated PLIN3 and Erlin1." (PMID 27045805, 2016). "In addition, human and murine studies have shown that miR-34a inhibited the liver secretion of very low-density lipoprotein (VLDL), causing steatosis when combined with hepatocyte nuclear factor 4 alpha (HNF4α)." (PMID 37371692, 2023). "This decrease in HNF4A expression was also confirmed via single-cell expression analysis of human hepatocytes from patients with low and mild steatosis." (PMID 39939782, 2025). "HNF4α depletion in hepatocytes dramatically increases sepsis lethality, steatosis, and organ damage and prevents an adequate response to IL6, which is critical for liver regeneration and survival." (PMID 39261648, 2024). "Deletion of HNF4α in the liver leads to hepatic lipid accumulation, severe steatosis, and even the development of fatty liver." (PMID 38346961, 2024). "This is consistent with literature showing Hnf4α activity is decreased by fatty acids and decreased Pparα results in enhanced steatosis." (PMID 36675277, 2023). "Other diet-based models of progressive NAFLD have shown that HNF4α is a central regulator of the progression of steatosis to nonalcoholic steatohepatitis (NASH) and in the development of NAFLD-related HCC." (PMID 37036981, 2023). "Similar to HNF4α-knockout mice, HNF1α knockout also leads to a fatty liver phenotype with increased fatty acid synthesis and steatosis in the liver." (PMID 32235813, 2020). "The accumulation of lycopene in rats with steatosis positively regulated the farnesoid X-activated receptor (FXR) and the hepatocyte nuclear factor 4 alpha (HNF4A), which have been suggested as preventive factors in relation to steatosis." (PMID 31330977, 2019). "The concentration of fatty acids, which act as HNF4α antagonists, in the nucleus, is unknown, but if it is related to the overall level of steatosis in a particular organ, that could affect the dose required for efficacy." (PMID 35087037, 2022). "Similarly, a fisetin (a plant flavonoid) treatment suppresses HFD-induced steatosis by upregulating the HNF4α expression and reducing oxidative stress, which further protects the individual from NAFLD progression." (PMID 35723304, 2022). "Generally, HNF4α has been shown to have protective effects on hepatis steatosis." (PMID 36362837, 2022). "Inhibition of the miR-21 expression alleviated steatosis by upregulation of the key regulators of lipid metabolism, such as hepatocyte nuclear factor 4 alpha (Hnf4a), forkhead box transcription factors (Foxa2 and Foxo1), Ppara, and the signal transducer and activator of transcription 3 (Stat3)." (PMID 35052690, 2021). "In DIO mice, NCT led to recovery of hepatic HNF4α expression and reduction of steatosis." (PMID 34117215, 2021). "HNF4α knockout mice exhibit severe hepatomegaly (enlarged liver) and steatosis." (PMID 32235813, 2020).
steatosis (continued). "In addition, in the HL group the accumulation of lycopene upregulated the genes FXR and HNF4A, which have been suggested as preventive factors in relation to steatosis." (PMID 30200543, 2018). "In fact, genetic ablation of HNF4A in a mouse model prompted severe hepatomegaly and steatosis." (PMID 29899848, 2018). "In addition, Hnf4a knock-out mice developed severe hepatomegaly and steatosis, resulting in premature death." (PMID 25774879, 2015). "As previously discussed, TM6SF2 gene knockout, inhibition of MDM2–ApoB interaction, HNF4α, GLS1 inhibition, and mTORC1 activation on VLDL lipidization have shown great potential for reducing steatosis by regulating VLDL to affect MASLD." (PMID 40723862, 2025). "Hepatic HNF4α expression was evaluated in sixteen control and thirty-three NAFLD (seven simple steatosis and twenty-six steatohepatitis) patients." (PMID 36362837, 2022). "Thus, it was logical to ask whether more potent HNF4α agonists could alleviate steatosis." (PMID 34117215, 2021). "Consequently, dysregulation of HNF4α- and COUP-TFII-signaling is likely involved, albeit through yet to be determined mechanisms, in the progression of steatosis to hepatotoxicity and steatohepatitis with fibrosis by TCDD." (PMID 35163483, 2022). "Taken together, we provide evidence that OF exhibits the anti‐HCC, anti‐steatosis, and anti‐fibrosis effect for liver in zebrafish models, and the anti‐cancer potential of OF attributed to the binding to ASGR and activation of STAT3/HNF4A signaling." (PMID 33377648, 2020). "The induction of CYP4A genes by a high fat diet leads to increased production of dicarboxylic acids that are potent inhibitors of HNF4α transactivation, which may contribute to the suppression of the CYP4F genes during steatosis." (PMID 20300478, 2009).
gastric cancer (37 papers, 2015 to 2026). A primary or metastatic malignant neoplasm involving the stomach. "In this study, we demonstrated that HNF4α expression in gastric cancer specimens was associated with patients' survival." (PMID 25965823, 2015). "Taken together, these data indicate that ITLN1 suppresses the progression of gastric cancer through up-regulation of HNF4α, and is associated with improved survival in patients with gastric cancer." (PMID 25965823, 2015). "It is also important to investigate recombinant omentin or HNF4α activators in preclinical models, such as patient-derived gastric-cancer organoids and xenografts." (PMID 41149627, 2025). "The group without ELF3/HNF4A up-regulation also had a higher percentage of early onset (diagnosis at age less than 50 years old) gastric cancers (21.4% vs. 4.3% in the group with ELF3/HNF4A up-regulation." (PMID 41425714, 2025). "A master regulator of the endoderm intestinal differentiation, HNF4α showed a strong co-expression with CDX2 at the mRNA level in the TCGA gastric cancer cohort." (PMID 39768557, 2024). "In 90 well-established primary samples from gastric cancer tissues, hepatocyte nuclear factor 4 alpha (HNF4α) expression correlated positively with omentin-1." (PMID 37568613, 2023). "ITLN1 treatment reduced the proliferation and the migratory ability of gastric cancer cells by upregulating hepatocyte nuclear factor 4α (HNF4a) via increased inhibition of nuclear factor kappa B (NFkB)." (PMID 35186726, 2022). "HNF4A is also a potential marker for distinguishing between primary gastric cancer and metastatic breast cancer." (PMID 35428183, 2022). "Functional enrichment of DEGs linked HNF-4α and HNF-1α genes as highly expressed in Cldn6high gastric cancer." (PMID 36430456, 2022). "For example, berberine has been shown to inhibit proliferation, migration, and invasion by targeting the AMPK/HNF4α/WNT5A pathway in gastric cancer cells." (PMID 33231372, 2021). "Since NF-κB suppresses the expression of hepatic nuclear factor 4 alpha (HNF4α), omentin-1 upregulates its expression in gastric cancer cells via attenuating NF-κB signaling." (PMID 34588926, 2021). "Hepatocyte nuclear factor 4α (HNF4A) has been demonstrated to be an oncogene in gastric cancer (GC)." (PMID 33710810, 2021). "What’s the molecular mechanism of HNF4α, a nuclear receptor that activates the expression of genes involved in glucose, fatty acid and cholesterol metabolism, in the development of gastric cancer?" (PMID 30405404, 2018). "It demonstrated that HNF4α was involved in the growth, invasion and metastasis capacity of gastric cancer." (PMID 30405404, 2018). "In general, including the HNF4A marker positively increased the evaluated indicators and enhanced the discrimination of primary gastric cancer and metastatic gastric cancer." (PMID 28583188, 2017). "Survival curves were plotted to compare patient outcomes in different expression levels of HNF4α and IL-1R1 and we found a reduction of survival time in patients with high co-expression levels of HNF4α and IL-1R1 in different types of gastric cancer." (PMID 26870992, 2016). "Our results reveal NF-κB, HNF4α and IL-1R1 are all part of the self-perpetuating circuit connecting gastritis to gastric cancer." (PMID 26870992, 2016). "We further examined HNF4α and IL-1R1 expression in 90 gastric cancer samples and corresponding normal tissues." (PMID 26870992, 2016). "Taken together, these results demonstrated that the expression of HNF4α and ITLN1 was positively correlated and associated with improved survival in clinical gastric cancer cases." (PMID 25965823, 2015). "Mechanistically, ITLN1 attenuated the activity of nuclear factor-kappa B, a transcription factor repressing the HNF4α expression, in gastric cancer cells through inactivating the phosphoinositide 3-kinase/AKT/Ikappa B kinase signaling." (PMID 25965823, 2015).
gastric cancer (continued). "Overall, these results demonstrated that ITLN1 considerably facilitated the HNF4α expression at transcriptional levels in gastric cancer cells." (PMID 25965823, 2015). "Our data showed that ITLN1 suppressed the activity of NFκB through inactivating PI3K/AKT/IKK pathway, resulting in increased HNF4α expression in gastric cancer cells." (PMID 25965823, 2015). "We demonstrated that ITLN1 increased the levels of hepatocyte nuclear factor 4 alpha (HNF4α), resulting in suppression of nuclear translocation and transcriptional activity of β-catenin in gastric cancer cells." (PMID 25965823, 2015). "Western blot and real-time quantitative RT-PCR were applied to measure the expression levels of ITLN1 and HNF4α in gastric cancer specimens, normal gastric mucosa, and cultured cell lines AGS, SGC-7901, MKN-28, and MKN-45." (PMID 25965823, 2015). "In this study, our experimental evidence demonstrated that HNF4α was a target of transcription factor NFκB in gastric cancer cells." (PMID 25965823, 2015). "In summary, for the first time, we have demonstrated that secretory ITLN1 efficiently inhibited the growth, invasion, and metastasis of gastric cancer cells in vitro and in vivo through up-regulating HNF4α in a PI3K/AKT/IKK/NFκB inactivation-dependent manner." (PMID 25965823, 2015). "Detailed dissection of the role of ELF3 and HNF4A in gastric cancer could be performed in studies using CRISPR or siRNA models." (PMID 41425714, 2025). "In gastric cancer, HNF4A expression is stronger than that in the adjacent unaffected mucosa." (PMID 41425714, 2025). "Amplifications of ERBB2 and CCND3 were significantly more frequent in ELF3/HNF4A up-regulated gastric cancers (28.6% and 20.4%, respectively) compared with the group of non-up-regulated cancers (2.4% and none, Student’s t-test p = 0.0006 and 0.001, respectively)." (PMID 41425714, 2025). "The family member ELF3 was well expressed in the mRNA level in a subset of gastric cancers (n = 91), and its expression correlated with the expression of other transcription factors involved in gastric cancer pathogenesis, including HNF4A, HNF1A, CDX2, GATA4, GATA6, and EHF." (PMID 41425714, 2025). "Furthermore, different HNF4α subtypes derived from two different promoters (P1 and P2) determine the malignancy degree in gastric cancer." (PMID 36249028, 2022). "The anti-gastric cancer mechanism of berberine may involve the HNF4α- AMPK-WNT5A signaling pathway and HNF4α is a key molecule target." (PMID 36144625, 2022). "HNF4α blocks the metastatic effects of β-catenin by inhibiting its nuclear translocation, a mechanism that accounts for the anti-metastatic effect of omentin-1 in gastric cancer cells." (PMID 34588926, 2021). "Moreover, it was reported that the anti-gastric cancer effect of metformin was related with the HNF4α inhibition through AMPK signaling." (PMID 30405404, 2018). "Moreover, many studies have found that HNF4α is highly expressed in gastric cancer tissues, especially in Asia." (PMID 30405404, 2018). "Secondly, the lentivirus infection was used to silence HNF4α in SGC7901 cell to demonstrate whether HNF4α was a key target for anti-gastric cancer." (PMID 30405404, 2018). "HNF4A alone could be a gold standard marker for distinguishing primary gastric cancer from breast metastasis, thus validating its potential clinical use, especially in populations with high genetic diversity." (PMID 28583188, 2017). "HNF4α can be a therapeutic target in early stage of gastric cancer." (PMID 26870992, 2016). "HNF4α and IL-1R1 showed an increasing trend along with the severity of atrophic gastritis already, which was in accordance with the results in mice, and were increased in gastric cancer samples." (PMID 26870992, 2016). "HNF4α was increased in gastric cancer compared with atrophic gastritis samples." (PMID 26870992, 2016). "HNF4α had a significant impact on cell proliferation in gastric cancer cell lines." (PMID 26870992, 2016).